CTCF (CCCTC-binding factor)
Diseases named in the same sentence as CTCF in open-access papers (continued):
Sharing a sentence is not in itself a finding about the gene and the disease.
hepatocellular carcinoma (16 papers, 2017 to 2025). A malignant tumor that arises from hepatocytes. "For example, CTCF upregulation was linked to advanced or metastatic disease and poor prognosis in hepatocellular carcinoma and ovarian cancers." (PMID 31736271, 2020). "Recent study has shown that exosomal JPX from hepatocellular carcinoma (HCC) cells promotes XIST expression by inhibiting the function of CCCTC-binding factor (CTCF) in blood cells." (PMID 31941509, 2020). "Other potentially altered loops include a CTCF site near BCL6 in hepatocellular carcinoma and breast adenocarcinoma, and CLCN4 in colorectal adenocarcinomas." (PMID 32024999, 2020). "Dysfunction of the TGF-β–regulated SPTBN1/SMAD3/CTCF complex increases stem cell–like properties in hepatocellular carcinoma (HCC) cells and enhances tumorigenesis in tumor-initiating cells in a mouse model." (PMID 33457451, 2020). "In the present study, we show that GR regulated ANGPTL4 in a CTCF-mediated chromatin context in the human hepatic carcinoma cell line HepG2." (PMID 28056052, 2017). "Here, we report that GR regulates ANGPTL4 in a CTCF-mediated chromatin context in the human hepatic carcinoma cell line HepG2." (PMID 28056052, 2017). "FOXM1 promoter is transcriptionally activated by CTCF in hepatocellular carcinoma." (PMID 35378133, 2022).
melanoma (16 papers, 2012 to 2026). A malignant, usually aggressive tumor composed of atypical, neoplastic melanocytes. "Reactivation of ERK signaling is mediated by deregulation of the expression of dual specificity phosphatase 6 (DUSP6), an inhibitor and regulator of ERK activity in melanoma, which is mediated by CCCTC-binding factor (CTCF) and by the loss of STAG2." (PMID 38672652, 2024). "ChIP-seq in melanoma cells revealed that CHD4 occupied an intronic regulatory element in PADI1 immediately adjacent to sites occupied by transcription factors CTCF and FOSL2 (AP1)." (PMID 33741961, 2021). "Mel-3 melanoma cells showed a reduced expression on CTCF gene upon 5AzaCdR combined with TSA treatment." (PMID 22984562, 2012). "To characterize the role of STAG2 in 3D genome organization in melanoma cells, we carried out ChIP-seq against STAG2, STAG1, SMC1A, and CTCF as well as Hi-C analyses in M14 melanoma cells stably expressing inducible shRNA of STAG26." (PMID 35388001, 2022). "CPEB3 is correlated with several critical pathways in melanoma, including PD1 signaling, CTLA4 pathway, CTCF pathway, CHEMOKIN signaling, VEGF signaling, and JAK-STAT pathway." (PMID 33506034, 2021). "Similarly, HiCDC+ showed higher differences than the edgeR settings for the Melanoma, IKAROS CTCF, and SMC1 HiChIP datasets, likely due to the method’s higher stringency." (PMID 41187750, 2025). "In addition, we observed increased CTCF expression in NSCLC, gastric cancer and melanoma tissues compared with the matching normal tissues." (PMID 28977939, 2017). "However, the significance of CTCF expression in NSCLC, gastric cancer and melanoma remains to be elucidated." (PMID 28977939, 2017).
colorectal cancer (15 papers, 2014 to 2024). A primary or metastatic malignant neoplasm that affects the colon or rectum. "Aberrant regulation of CTCF expression is associated with occurrence of cancers, such as colorectal carcinoma." (PMID 24626568, 2014). "CTCF interacts with telomeric repeat binding factor 2 (TRF2) to promote the proliferation of colorectal cancer." (PMID 38436544, 2024). "Chromatin remodeler CTCF has been shown to be upregulated in colorectal cancer tissue, and the overexpression of CTCF promoted colorectal cancer cell proliferation." (PMID 37938151, 2023). "Findings obtained from a study confirmed that CTCF is upregulated in colorectal cancer cells and elevated CTCF is able to promote drug resistance in colorectal cancer." (PMID 35693981, 2022). "The overexpression of CTCF promoted colorectal cancer cell proliferation and tumor growth, while the opposite effects were observed in CTCF knockdown cells." (PMID 32688344, 2020). "In colorectal cancer CTCF alterations are observed overall in 11.24% of cases and mutations are less frequent (4.87%)." (PMID 30275357, 2018). "However, suppressing CTCF in human colorectal cancer cell line HCT116 notably reduced HOXA7 and HOXA9 expression, consistent with the finding in MLLr AML cell line MOLM13." (PMID 33001025, 2020). "Here, we identified a tumor-promoting role for CTCF in colorectal cancer." (PMID 32688344, 2020). "CTCF is overexpressed in several cancers and plays crucial roles in regulating aggressiveness, but little is known about whether CTCF drives colorectal cancer progression." (PMID 32688344, 2020). "In colorectal cancer cells, a study noted that CCAT1 was located within a super-enhancer and interacted with CTCF protein to maintain chromatin looping between the MYC promoter and its enhancers, resulting in elevated expression of MYC33." (PMID 30190462, 2018). "Depletion of CTCF altered the genome-wide TAD insulation and resulted in disruption of phase separated transcriptional condensates in colorectal cancer cells, indicating that CTCF-mediated DNA looping provides a spatial architecture and essential for the formation of transcriptional condensates." (PMID 35966880, 2022). "Our study demonstrated that CTCF was upregulated in colorectal cancer specimens compared with adjacent noncancerous colorectal tissues." (PMID 32688344, 2020). "In addition, lncRNA CCAT1-L together with CTCF can mediate a 335-kb interaction between the MYC promoter and its enhancer in colorectal cancer." (PMID 29149895, 2017).
endometrial cancer (15 papers, 2014 to 2025). Primary or metastatic malignant neoplasm involving the endometrium (mucous membrane that lines the endometrial cavity). "Hemizygous deletions of CTCF are prevalent in prostate, ovarian, and breast cancers, while its allelic loss in kidney and endometrial cancers is associated with decreased patient survival." (PMID 38374872, 2024). "While the overexpression of CTCF blocks cell growth by slowing down the cell cycle, some point mutations in CTCF that lead to gain of CTCF function can enhance cell survival by blocking apoptosis, as in the case of endometrial carcinomas." (PMID 35993175, 2022). "CTCF is a significantly mutated gene in ~ 20% of endometrial cancers and is recurrently mutated in myeloid and lymphoid malignancies." (PMID 34657170, 2021). "The two inter-ZF mutations (R377H and P378L) abrogated CTCF’s anti-proliferative and anti-clonogenic effect in Ishikawa endometrial cancer cells." (PMID 34657170, 2021). "CTCF encoding a highly conserved 11-zinc finger DNA binding protein is mutated in about 15% of endometrial cancer." (PMID 30886832, 2019). "CTCF has been classified as a significantly mutated gene owing to its high frequency of mutation and deletion in endometrial cancer." (PMID 30513694, 2018). "Examination of CTCF mutations in endometrial cancers showed locus-specific alterations in gene expression due to CTCF haploinsufficiency, in concert with downregulation of tumour suppressor genes and upregulation of estrogen-responsive genes." (PMID 30513694, 2018). "In this study we assessed several genetic models of CTCF haploinsufficiency to reveal in detail the impact of heterozygous loss of CTCF in somatic cells, whole mice and human endometrial cancer." (PMID 30513694, 2018). "A recurrent CTCF mutation in the N-terminal domain of CTCF in endometrial carcinomas observed in six samples was a frameshift mutation at codon T204 producing truncation of the protein after 18 or 26 amino acids." (PMID 30275357, 2018). "CTCF mutations are detected in 35% of endometrial carcinomas exhibiting microsatellite instability (MSI), and in 20% of MSI-negative tumours." (PMID 30513694, 2018). "CTCF mutations in endometrial carcinomas lead to nonsense-mediated decay of the transcripts or loss of function of the protein with missense mutations." (PMID 30275357, 2018). "Despite our demonstration of a gain-of-function mutation in CTCF, the majority of CTCF mutations in endometrial cancer result in loss-of-function." (PMID 28319062, 2017). "Inactivation of one allele of CTCF (CTCF haploinsufficiency) effectively reduces the amount of functional CTCF in endometrial cancer cells." (PMID 28319062, 2017). "As CTCF is a significantly mutated gene in endometrial cancer, we sequenced CTCF in five endometrial cancer cell lines and identified four mutations." (PMID 28319062, 2017). "Conversely the majority of endometrial cancer-associated genetic changes to CTCF result in inactivation of one allele of CTCF leading to haploinsufficiency." (PMID 28319062, 2017). "Here we show that CTCF mutations identified in primary human endometrial carcinoma predominantly showed loss-of-function phenotypes due to nonsense-mediated decay of mutant transcripts or abrogation of functional activity." (PMID 28319062, 2017). "As the majority of CTCF mutations identified in endometrial carcinoma effectively result in inactivation of one CTCF allele, we modelled this using inducible shRNA knockdown of CTCF." (PMID 28319062, 2017).
endometrial cancer (continued). "Additionally, a tumor‐suppressive role for CTCF has been posited, particularly as a myriad of genetic aberrations, including the loss of one CTCF allele, have been implicated as oncogenic drivers in breast and endometrial cancers." (PMID 38374872, 2024). "Interestingly, our previous endometrial cancer study indicated that missense ZF-containing CTCF alleles were expressed at a higher frequency than WT alleles, when comparing RNA sequencing to DNA sequencing." (PMID 34657170, 2021). "For instance, by stratifying endometrial carcinoma cell lines based on mutations in both CTCF and ZFHX3, we observed a pattern of differential response to microtubule inhibitors, and this pattern would not have been apparent if we stratified cell lines based on mutations in individual genes." (PMID 31253832, 2019). "Importantly, the type of cancer that stands out as having the highest mutation rate of CTCF is endometrial cancer, where CTCF is mutated in more than one fourth of tumours (27.45%)." (PMID 30275357, 2018). "Importantly, expression levels of the tumour suppressor genes CDKN2A and PIK3CA, which are deleted or mutated in endometrial cancer, were decreased in CTCF-altered samples (p = 0.0006 and p = 0.0007, respectively)." (PMID 30513694, 2018). "Since CTCF is known to co-ordinate higher-order chromatin architecture to facilitate interactions between transcription regulatory sequences, our data reinforces the impact that CTCF haploinsufficient loss imparts in endometrial cancer via transcriptional regulation." (PMID 30513694, 2018). "Among 91 different CTCF mutations found in endometrial carcinoma in TCGA, 45 (49.45%) are listed as likely oncogenic (the rest has unknown oncogenic potential and some of them may prove to be oncogenic as data accumulate)." (PMID 30275357, 2018). "In addition, we have shown that CTCF haploinsufficiency also occurs in poor prognosis endometrial clear cell carcinomas and has some association with endometrial cancer relapse and metastasis." (PMID 28319062, 2017). "Interestingly HEC1B, which is a sub-strain of HEC1A isolated from a patient with grade II endometrial cancer, has acquired an additional somatic mutation in CTCF, G19*." (PMID 28319062, 2017). "CTCF mutation is restricted to the endometrioid subtype of endometrial carcinoma, while genetic deletion of Ch16q including the CTCF locus, occurs predominantly in worse prognosis subtypes including serous carcinoma, and our preliminary studies indicate clear cell carcinoma." (PMID 28319062, 2017). "Interestingly, CTCF appears to be a target for slippage mutations in endometrial cancers with microsatellite instability." (PMID 25487306, 2015). "CTCF expression was decreased in a substantial proportion of endometrial cancer samples, some of which can be directly attributed to genetic deletion of CTCF (deep deletion)." (PMID 30513694, 2018). "In human endometrial cancer datasets, we identified a unique gene signature in CTCF haploinsufficient cancers arising from differential gene expression at specific loci." (PMID 30513694, 2018). "We since revealed that CTCF genetic alterations have a pro-tumourigenic effect in endometrial cancer by altering cellular polarity and enhancing cell survival." (PMID 30513694, 2018). "Genes involved in DNA methylation were also differentially regulated in CTCF-altered endometrial cancers." (PMID 30513694, 2018).
endometrial cancer (continued). "IGF2BP2, which was the most down-regulated gene in CTCF-altered endometrial cancer, was identified as a candidate tumour suppressor gene in a pan-cancer screen for homozygously deleted genes." (PMID 30513694, 2018). "We then analysed other gene mutations that co-occurred with or were mutually exclusive in CTCF-altered endometrial cancers." (PMID 30513694, 2018). "We also analysed the impact of CTCF haploinsufficiency by examining gene expression changes in CTCF-altered endometrial carcinoma." (PMID 30513694, 2018). "CTCF knockdown to recapitulate haploinsufficiency resulted in deregulation of endometrial cancer spheroid polarity which likely contributes to endometrial cancer development and progression." (PMID 28319062, 2017). "CTCF knockdown in the KLE endometrial cancer cell line reduces the proportion of endometrial cancer spheroids showing central luminal staining of apical polarity markers." (PMID 28319062, 2017). "Overall, we have identified two novel pro-tumorigenic roles (promoting cell survival and altering cell polarity) for genetic alterations of CTCF in endometrial cancer." (PMID 28319062, 2017). "We next determined if somatic copy number alterations in CTCF occurred in endometrial carcinoma (as estimated by GISTIC from within the TCGA portal)." (PMID 28319062, 2017). "Previous studies have shown that both RAD21 and CTCF are deregulated or aberrantly expressed in endometrial cancer." (PMID 25487306, 2015). "We analysed RNAseq data available for these endometrial cancer samples and showed that CTCF gene expression was not significantly decreased in CTCF-altered cancers despite the presence of inactivating mutations." (PMID 30513694, 2018). "Furthermore, the expression of estrogen-responsive genes KIAA1324, MLPH, MSX2, SPDEF, TFF3, and PIGR were all significantly up-regulated in CTCF-altered endometrial cancers (p = 0.0004, 0.0007, 0.0032, 0.0009, 0.0122, and 0.0028 respectively)." (PMID 30513694, 2018). "KIAA1324, which is a positive regulator of the autophagy pathway and may protect cells from cell death, was the most upregulated gene in CTCF-altered endometrial cancer." (PMID 30513694, 2018). "In endometrial cancer, CTCF mRNA transcripts expressed from alleles containing nonsense or frameshift mutations are subjected to nonsense-mediated decay." (PMID 30513694, 2018). "This epigenetic dysregulation may offer an explanation as to why differential gene expression was observed at particular chromosomal loci in CTCF-altered endometrial cancers." (PMID 30513694, 2018). "Downregulation of tumour suppressor genes and upregulation of estrogen-responsive genes may be a molecular feature of CTCF-altered endometrial cancers." (PMID 30513694, 2018). "CTCF genetic alterations in endometrial cancer indicate that gene dysregulation is a likely consequence of CTCF loss, contributing to, but not solely driving cancer growth." (PMID 30513694, 2018). "Finally, we examined curated human endometrial carcinoma genomic data and observed that CTCF haploinsufficiency contributed to the transcriptional dysregulation of specific loci as well as inducing a unique gene signature in human cancers." (PMID 30513694, 2018). "Furthermore, our copy number variation analysis of primary human endometrial cancers demonstrates that CTCF deletion occurs more commonly in tumours with a propensity for relapse or metastasis, and in tumours with clear cell histology." (PMID 28319062, 2017). "Analysis of previously published CTCF data in endometrial cancer: ADM, CGB, RJ, LD and EM." (PMID 28319062, 2017).
endometrial cancer (continued). "We report for the first time, that CTCF and CTCFL/BORIS seem to diverge in the different subtypes of endometrial cancer; with CTCF mutations occurring in endometrioid subtype and aberrant expression of CTCFL/BORIS being defined to cases of non-endometrioid subtype." (PMID 24658009, 2014). "Other estrogen-responsive genes upregulated in CTCF-altered cancers, namely SPDEF, TFF3 and PIGR, are also components of these gene signatures, indicating that loss of CTCF could be an important factor determining endometrial cancer progression and pathology." (PMID 30513694, 2018). "Only the KLE endometrial cancer cell line did not contain any CTCF mutations." (PMID 28319062, 2017). "Also, either CTCF overexpression or knockdown inhibit colony formation in endometrial cancer cells." (PMID 28319062, 2017). "Consequently, these result in a significant reduction in CTCF gene expression, indicating that haploinsufficient deletion of CTCF may be important in endometrial carcinoma pathogenesis and/or progression." (PMID 28319062, 2017). "The detection of specific mutations in genes such as PTEN, PIK3R1, CTCF, and BRAF, which correlate with advanced disease features like high-grade tumors and deep myometrial infiltration, suggests that cfDNA analysis could become a crucial tool in the clinical management of endometrial cancer." (PMID 40227624, 2025). "Our endometrial carcinoma analysis offered especially interesting results as it returned numerous pairs of networks with similarity, where most of the corresponding genes in these pairs - such as CTCF, NAV3, and ZFHX3 - are not typically implicated as markers of drug response." (PMID 31253832, 2019). "Thus, CTCF and CTCFL/BORIS are found to diverge in the different subtypes of endometrial cancer, with CTCFL/BORIS activation through demethylation from precursors to metastatic lesions." (PMID 24658009, 2014).